RNU1-54P (RNA, U1 small nuclear 54, pseudogene)
Gene: Small nuclear RNA gene on chromosome 6 (39,620,345 to 39,620,464, reverse strand). Ensembl gene ENSG00000252990.
Homologues: Orthologues: mouse Gm24192 (70% identical). Paralogues in human: RNU1-78P (75% identical), RNU1-115P (74% identical), RNU1-131P (74% identical), RNU1-32P (74% identical), RNU1-89P (74% identical), RNVU1-1 (74% identical), RNVU1-2 (74% identical), RNU1-1 (73% identical), RNU1-119P (73% identical), RNU1-18P (73% identical), RNU1-2 (73% identical), RNU1-21P (73% identical), and 134 more.